GBP5 (guanylate binding protein 5)
Description:
Interferon (IFN)-inducible GTPase that plays important roles in innate immunity against a diverse range of bacterial, viral and protozoan pathogens (By similarity). Hydrolyzes GTP, but in contrast to other family members, does not produce GMP. Following infection, recruited to the pathogen-containing vacuoles or vacuole-escaped bacteria and acts as a positive regulator of inflammasome assembly by promoting the release of inflammasome ligands from bacteria (By similarity). Acts by promoting lysis of pathogen-containing vacuoles, releasing pathogens into the cytosol (By similarity). Following pathogen release in the cytosol, promotes recruitment of proteins that mediate bacterial cytolysis: this liberates ligands that are detected by inflammasomes, such as lipopolysaccharide (LPS) that activates the non-canonical CASP4/CASP11 inflammasome or double-stranded DNA (dsDNA) that activates the AIM2 inflammasome (By similarity). As an activator of NLRP3 inflammasome assembly: promotes selective NLRP3 inflammasome assembly in response to microbial and soluble, but not crystalline, agents. Independently of its GTPase activity, acts as an inhibitor of various viruses infectivity, such as HIV-1, Zika and influenza A viruses, by inhibiting FURIN-mediated maturation of viral envelope proteins. Antigenic tumor-specific truncated splice form.
Synonyms: GBP-5
Tractability: Small molecule: a structure with a bound ligand is known. PROTAC: ubiquitination databases record sites on it; its protein half-life has been measured.
Gene: Protein-coding gene on chromosome 1 (89,256,189 to 89,272,890, reverse strand). Ensembl gene ENSG00000154451.
Subcellular location: Cytoplasmic vesicle membrane; Golgi apparatus membrane; Cytoplasm
Pathways (Reactome):
Immune System: GBP-mediated host defense; Interferon gamma signaling
Gene Ontology:
Molecular function: GTPase activity; identical protein binding; molecular function inhibitor activity; protein binding; protein homodimerization activity; GTP binding
Biological process: cellular response to type II interferon; defense response to virus; positive regulation of interleukin-1 beta production; positive regulation of NLRP3 inflammasome complex assembly; protein homotetramerization; protein localization to Golgi apparatus; cytolysis in another organism; positive regulation of AIM2 inflammasome complex assembly; positive regulation of cytokine production involved in inflammatory response; positive regulation of innate immune response; positive regulation of interleukin-18 production; positive regulation of pyroptotic inflammatory response; activation of innate immune response; cellular response to lipopolysaccharide; defense response to bacterium; protein targeting
Cellular component: cytoplasm; Golgi apparatus; Golgi membrane; membrane; perinuclear region of cytoplasm; cytoplasmic vesicle; cytoplasmic vesicle membrane; cytosol; symbiont cell surface
Genetic constraint (gnomAD): Loss-of-function variants: 31 observed, 47.83 expected, observed/expected ratio (o/e) 0.65, 90% interval 0.49 to 0.88. The upper end of that interval is the gene's LOEUF score, 0.88, which puts it in group 3 of 6, group 1 being the genes least tolerant of losing a copy. Missense variants: 634 observed, 643.35 expected, observed/expected ratio (o/e) 0.99, 90% interval 0.92 to 1.05. Synonymous variants: 226 observed, 239.49 expected, observed/expected ratio (o/e) 0.94, 90% interval 0.85 to 1.05.
Homologues: Orthologues: chimpanzee GBP5 (98% identical), pig GBP5 (67% identical), rat Gbp5 (67% identical), mouse Gbp5 (67% identical), Drosophila melanogaster atl (19% identical). Paralogues in human: GBP3 (68% identical), GBP1 (67% identical), GBP2 (64% identical), GBP7 (51% identical), GBP4 (51% identical), GBP6 (50% identical), ATL3 (20% identical), ATL2 (19% identical), ATL1 (19% identical), RNF112 (12% identical).
Diseases named in the same sentence as GBP5 in open-access papers:
GBP5 is named in the same sentence as 115 diseases in open-access papers, as found by Europe PMC text mining. Sharing a sentence is not in itself a finding about the gene and the disease. The quoted sentences say what the papers report.
tuberculosis (14 papers, 2018 to 2025). A chronic, recurrent infection caused by the bacterium Mycobacterium tuberculosis. "For example, in tuberculosis, an infectious disease caused by Mtb, GBP5 expression varies markedly: some studies report significant upregulation in active pulmonary tuberculosis, supporting its potential as a diagnostic marker, while others observe downregulation in similar patient populations." (PMID 40788157, 2025). "Expression of the 3-gene signature, [guanylate-binding protein (GBP5), dual specificity phosphatase 3 (DUSP3) and Krupple-like factor 2 (KLF2)] was quantified and a tuberculosis (TB) score was calculated using (GBP5+DUSP3)/2-KLF2." (PMID 41430759, 2025). "Nevertheless, a difference seems plausible considering the pathophysiology of diseases: the GBP5 gene, which codes a GTPase, is involved in interferon-induced pro-inflammatory responses and is a key gene in active tuberculosis." (PMID 38245113, 2024). "The aim of this study was to investigate whole blood GBP5 protein levels in aTB and non-tuberculosis patients." (PMID 35369870, 2022). "Here, a three-gene set (GBP5, DUSP3, and KLF2) in the host whole blood that is robustly diagnostic for active tuberculosis was studied using multiple independent cohorts comprised of children and adults." (PMID 36010011, 2022). "The host blood transcriptional levels of several genes, such as guanylate binding protein 5 (GBP5), have been reported as potential biomarkers for active tuberculosis (aTB) diagnosis." (PMID 35369870, 2022). "The GBP5 protein levels of aTB patients were significantly higher than those of non-tuberculosis patients (p < 0.001), and the area under the ROC curve of the GBP5 assay for aTB diagnosis was 0.76." (PMID 35369870, 2022). "Another meta-analysis, using a total of 14 datasets identified a different set of three genes (GBP5, DUSP3, and KLF2) that were highly diagnostic for active tuberculosis in HIV infected and uninfected populations." (PMID 29764370, 2018). "In tuberculosis, GBP5 expression demonstrates variable patterns." (PMID 40788157, 2025). "Moreover, recent findings demonstrate that GBP5 effectively distinguishes active tuberculosis from other respiratory diseases, LTBI, and healthy controls." (PMID 40788157, 2025). "Consequently, GBP5 emerges as a promising biomarker for clinical tuberculosis diagnosis and the monitoring of treatment response." (PMID 38935691, 2024). "Given GBP5’s complex mechanisms and broad therapeutic implications, future research should prioritize: (i) Dynamic Profiling: Investigating GBP5 expression across varying immune backgrounds, disease stages, and conditions such as tuberculosis and IBD to refine its role as a biomarker." (PMID 40788157, 2025). "The expression levels of certain genes related to anti-tuberculosis were further confirmed, such as CCL1, IL15, IL16, ISG15, GBP5, IL23, ATG2A, IFNβ, and CSF3." (PMID 38392218, 2024). "Subsequently, we further verified the transcription levels of genes on anti-tuberculosis-related genes such as CCL1, IL15, IL16, ISG15, GBP5, IL23, ATG2A, IFNβ, and CSF3." (PMID 38392218, 2024). "Rv1476 overexpression inhibited the expression of some anti-tuberculosis-related genes, such as CCL1, IL15, IL16, ISG15, GBP5, IL23, ATG2A, IFNβ, and CSF3." (PMID 38392218, 2024). "Many interferon pathway-related genes, including STAT1,GBP1,GBP5, IFI44, IFIH1, FITM3, have been described in whole-blood transcriptome studies of tuberculosis." (PMID 36059536, 2022). "A novel 3-gene host transcriptional signature (GBP5, DUSP3 and KLF2) has been validated for tuberculosis (TB) treatment monitoring using laboratory-based RNA sequencing platforms." (PMID 34193258, 2021). "Then, we investigated the difference in GBP5 protein levels between aTB and non-tuberculosis (non-TB) patients." (PMID 35369870, 2022).
tuberculosis (continued). "When combined with four additional genes (LTF, guanylate binding protein 5, CD64, and Granzyme A), FCGRIB demonstrated the ability to effectively differentiate between TB disease and latent tuberculosis infection (LTBI) in small case-control investigations." (PMID 39097795, 2024). "They specifically focused on comparing the expression profiles of three genes – guanylate binding protein 5, granzyme A, and CD64 – in blood specimens obtained from patients diagnosed with TB disease, non-tuberculosis pneumonia, or Asthma." (PMID 39097795, 2024).
viral infection (13 papers, 2017 to 2025). "GBP5 plays a central role in cell signaling, particularly during viral infections, partly through the activation of the NF-κB signaling pathway." (PMID 40788157, 2025). "Specifically, spermine has been shown to reduce IL-1β in acute liver injury, suppress NLRP3 inflammasome activation in diabetic atherosclerosis, and downregulate Guanylate Binding Protein 5 (GBP5)-mediated NLRP3 activation during viral infection." (PMID 41463524, 2025). "In viral infections, GBP5 expression increases significantly in A549 human lung epithelial cells infected with the influenza virus, where it augments virus-induced IFN production and suppresses viral replication." (PMID 40788157, 2025). "To confirm these findings in the context of authentic virus infection, we examined the effect of GBP5 or GBP5-C583A overexpression on S protein processing and infection with SARS-CoV-2 in HEK 293T cells expressing the SARS-CoV-2 co-receptors ACE2 and TMPRSS2." (PMID 38746287, 2024). "We find that optimal classifiers include an interferon-stimulated gene that is strongly induced in COVID-19 compared with nonviral conditions, such as IFI6, and a second immune-response gene that is more strongly induced in other viral infections, such as GBP5." (PMID 36507688, 2023). "Furthermore, viral infection increased the mRNA expression of cytokines (Il6, Tnf), chemokines (Cxcl10, Ccl2), and interferon-responsive genes (Ifnb1, Ifit3, Irf7, Gbp5 and Isg15)." (PMID 37081549, 2023). "Here, we report that GBP2 and GBP5 inhibit the cleavage of SARS-CoV-2 spike and reduce viral infection." (PMID 36693093, 2023). "The immunity-related proteins Mib1, RhoB and Gbp5 became more abundant in macrophage lysosomes after treating with L. m, HSV-1 or VSV, while lysosomal Oasl2 (Viperin) was augmented by both virus infections." (PMID 28088779, 2017). "Unlike its regulatory role in bacterial and viral infections, GBP5 exerts more direct antiparasitic effects, underscoring its therapeutic potential in parasitic diseases." (PMID 40788157, 2025). "GBP5 promotes NLRP3 (NOD-like receptor protein 3) inflammasome assembly, an inflammasome known to play a critical role in the innate immune response against parasitic, fungal, bacterial, and viral infections 43,44." (PMID 41473269, 2025).
breast carcinoma (9 papers, 2013 to 2025). "While GBP-5 has been associated with improved prognosis in breast cancers, one group of investigators published that GBP-5 correlated with good prognosis in TNBC samples and then used a different set of array data to suggest it correlated with poor prognosis." (PMID 35681772, 2022). "GBP5 has been reported to be associated with tumor immune invasion in basal-like breast cancer and hepatocellular carcinoma." (PMID 36246628, 2022). "Recently, three members of the Guanylate-Binding Protein (GBP) family of interferon-induced GTPases, GBP-1, GBP-2, and GBP-5, have been implicated to play roles in breast cancer." (PMID 35681772, 2022). "Particularly, GBP5 upregulation was significantly associated with a pCR rate in breast cancer patients receiving docetaxel/paclitaxel-based neoadjuvant therapy." (PMID 33809079, 2021). "Suppressing GBP5 boosts chemotherapy efficacy in breast cancer, enhancing taxane response and reducing immune evasion, quantifiable through apoptosis assays, immune profiling, or tumor size reduction metrics, aiding treatment monitoring." (PMID 40564939, 2025). "To clarify what we do and do not know about GBPs in breast cancer, the current literature on GBP-1, GBP-2, and GBP-5 in breast cancer has been assembled." (PMID 35681772, 2022). "Once again, however, there are some disparities in descriptions of the role of GBP-5 in breast cancers." (PMID 35681772, 2022). "Since TNBC is a highly metastatic subtype of breast cancer, we next determined the correlation between GBP5 expression and cellular migration ability in the TNBC cell lines HCC1937, HCC1806, Hs578T and MDA-MB-231." (PMID 33916322, 2021). "Accordingly, in breast cancer cohort received paclitaxel neoadjuvant therapy, GBP5 upregulation significantly (p < 0.001) referred to a pathologic complete response." (PMID 33809079, 2021). "STAT1 plays a key role in regulating the effect of chemotherapy; TYMP is considered to be a potential prognostic marker for ovarian cancer and breast cancer; GBP5, as an immune response regulator, can affect tumor progression; and PSME2 is closely related to the progression of various tumors." (PMID 40259929, 2025). "Of the GBPs involved in breast cancer, the least is known about the function of GBP-5." (PMID 35681772, 2022). "GBP-5 is correlated with improved prognosis in TNBCs and ER− breast cancers but the molecular activities of GBP-5 that contribute to this are unknown." (PMID 35681772, 2022). "Three of the members of this family are associated with breast cancer: GBP-1, GBP-2, and GBP-5." (PMID 35681772, 2022). "Notably, a higher level of GBP5 appeared to correlate with a shorter time period for brain metastasis in breast cancer patients." (PMID 33916322, 2021). "Importantly, the signature of combining higher GBP5 and PD-L1 predicted a shorter time period for brain metastasis in breast cancer patients." (PMID 33916322, 2021). "Importantly, the signature combining a higher GBP5 and PD-L1 level predicted the shortest time interval of brain metastasis in breast cancer patients." (PMID 33916322, 2021). "Importantly, the signature combining high-level GBP5 and PD-L1 transcripts predicted the shortest time interval for brain metastasis in breast cancer patients from the GSE11276 dataset." (PMID 33916322, 2021). "Pairing GBP inhibitors with chemotherapy (e.g., paclitaxel, temozolomide) or immune checkpoint blockers (e.g., PD-L1, CTLA-4) could overcome resistance, as seen with GBP5 in breast cancer and GBP3 in glioblastoma—a strategy testable in clinical trials or preclinical models." (PMID 40564939, 2025). "GBP-5 promotes NLRP3 inflammasome assembly, but it is unclear how that influences breast cancer prognosis." (PMID 35681772, 2022). "Our results showed that GBP5 expression in TNBC is predominantly higher than that in non-TNBC and normal mammary tissues and is a poor prognostic marker in breast cancer patients." (PMID 33916322, 2021).
breast carcinoma (continued). "Here, we found that guanylate binding protein 5 (GBP5) is expressed in higher levels in TNBC tissues than in non-TNBC and normal mammary tissues and serves as a poorer prognostic marker in breast cancer patients." (PMID 33916322, 2021). "The correlation with DMFS suggests that GBP-5 inhibits breast cancer metastasis but there is no data on GBP-5 function to confirm that." (PMID 35681772, 2022). "Whether GBP-5 correlates with improved DMFS in TNBC remains unclear due to probe set discrepancies, although it appears to do so for ER− breast cancers." (PMID 35681772, 2022). "Microarray analysis of Ifn-γ/Jak/Stat1 effector genes, such as Gbp1 and Gbp5, have grouped the pathway with estrogen receptor negative (ER-) and triple-negative (ER−/PR/Her2-) breast cancers." (PMID 23520493, 2013). "Both GBP-1 and GBP-5 are suggested to be potential drug targets in breast cancers, despite that there is no consensus on whether they are associated with better or worse prognoses." (PMID 35681772, 2022). "Like GBP-1, GBP-5 is not a good prognostic indicator in ER+ breast cancers." (PMID 35681772, 2022). "Unlike GBP-1, GBP-5 correlates with improved RFS and OS as a single gene in a cohort containing all breast cancers." (PMID 35681772, 2022). "Unlike GBP-1 and GBP-5, all the literature on GBP-2 and breast cancer indicates that it is protective." (PMID 35681772, 2022).
glioblastoma (8 papers, 2018 to 2025). The most malignant astrocytic tumor (WHO grade IV). "GBP2 and GBP5 are interferon-inducible guanylate-binding proteins, acting in innate immunity and exerting a tumor-sustaining function in glioblastoma." (PMID 40498028, 2025). "GBP5 promotes glioblastoma matrix degradation via Src/ERK1/2/MMP3, aiding vascular co-option and metastatic progression, linked to its Golgi-based signaling and immune modulation." (PMID 40564939, 2025). "The recent publication of a paper suggesting GBP-5 drives glioblastoma malignancy suggests that cell type and cellular environment will be important." (PMID 35681772, 2022). "Previous studies have shown that GBP5 can promote the malignant progression of oral squamous cell carcinoma, triple-negative breast cancer, and glioblastoma." (PMID 36246628, 2022). "Additionally, guanylate-binding protein 5 (GBP5) promotes glioblastoma malignancy through the SRC/ERK1/2/MMP3 pathway, implicating ETS1 and MMP3 as downstream effectors of SRC signaling." (PMID 41462902, 2025). "The increased expression level of GBP1 was associated with EGFR amplification in glioblastoma multiforme patients with poor prognosis, implying that EGFR signaling might also be required for GBP5 induction in OSCC." (PMID 34439200, 2021). "Indeed, both genes may be overexpressed in glioblastoma compared with healthy tissue, and higher levels of GBP5 expression are correlated with a worse prognosis." (PMID 40498028, 2025). "According to the literature, among the genes whose expressions change after treatment and have an LTR12C element at the TSS site, only IRGM, GBP2, GBP5, and TP63 are known to play a meaningful role in glioblastoma." (PMID 40498028, 2025). "GBP5 supports positive outcomes in endometrial, ovarian, and colorectal cancers, often through immune infiltration, but accelerates malignancy in stomach cancer via a JAK1-STAT1/GBP5/CXCL8 positive feedback loop and in glioblastoma via Src/ERK1/2/MMP3 signaling." (PMID 40564939, 2025).